FUT4 (fucosyltransferase 4)
Diseases named in the same sentence as FUT4 in open-access papers (continued):
Sharing a sentence is not in itself a finding about the gene and the disease.
lung carcinoma (continued). "In this study, for the first time, we found that Rg3 effectively inhibited migration, invasion, EMT and metastasis by down-regulating FUT4 in human lung cancer in vitro and in vivo." (PMID 26636541, 2016). "Rg3 also down-regulated FUT4 gene and protein expression in lung cancer cells by qPCR, Western blot and immunofluorescence." (PMID 26636541, 2016). "Among these FUTs, FUT4 catalyzes the synthesis of α1, 3-fucosylation of Lewis Y. Several reports have shown that FUT4 is overexpressed in many types of cancer, including colorectal, gastric and lung cancer." (PMID 26094873, 2015). "FUT4 is correlated with higher metastatic potentials in lung cancer." (PMID 36135043, 2022). "Additionally, FUT4 also correlates with a worse prognosis in lung cancer patients and upregulates EMT, vesicular trafficking, and lung cancer invasion." (PMID 35563790, 2022). "Furthermore, these two natural SLs suppressed MALAT1 expression, STAT3 activation, and FUT4 and P-GP expression which are the hallmarks for paclitaxel resistance in A549 lung cancer cells." (PMID 35281907, 2022). "Meanwhile, fucosyltransferase IV (FUT4) amounts are frequently elevated in lung cancer and may be related to increased chemoresistance." (PMID 32948132, 2020). "FUT4 may constitute an effective sensitization target in developing cisplatin-based chemotherapies for lung carcinoma." (PMID 32948132, 2020). "Elevated expression levels of Lewis Y and FUT4 are observed in lung cancer; however, whether FUT4 affects the chemosensitivity of NSCLC remains unclear." (PMID 32948132, 2020). "What is more, Rg3 is an important inhibitory EMT agent by targeting FUT4 in lung cancer." (PMID 30915362, 2019). "FUT4 expression in lung cancer tissues was higher than that in normal lung tissues (P < 0.001)." (PMID 26636541, 2016). "Consequently, Leo may function as a crucial pharmaceutical agent inhibiting EMT by targeting FUT4 in lung carcinoma, possessing the potential to impede tumor proliferation by suppressing EGFR and its downstream signaling pathways." (PMID 37818195, 2023). "In addition, a high expression of FUT4 was closely correlated with EMT in lung cancer." (PMID 26636541, 2016). "The current work sought to provide novel insights into the functional response of MALAT1 and efficacy of common members of SLs (ALT and Brv-A) in paclitaxel-resistant lung cancer, vis-à-vis MALAT1/STAT3 and MALAT1/FUT4 axis." (PMID 35281907, 2022). "CD15 and CD15s interact with CD62E to promote lung cancer cell adherence to the brain endothelium, exhibiting features comparable to white blood cells but interfering with FUT4/CD15 and FUT7/CD15s can inhibit CTCs invasion." (PMID 35251014, 2022). "M2 macrophages have been shown to induce EMT in lung cancer cells through TGF-β release which, in turns, up-regulated FUT4 and Ley antigen expression on ezrin receptor of cancer cells." (PMID 34356834, 2021). "Knockdown of FUT4/CD15 and FUT7/CD15s significantly reduced the number of adherent metastatic and primary lung cancer cells as well as GBM cells to brain endothelium." (PMID 31104223, 2019). "Taken together, these results suggest that down-regulating FUT4 expression decreased LeY biosynthesis which leads to the inhibition of EGFR activation, the downstream MAPK and NF-κB signal pathways in lung cancer cells." (PMID 26636541, 2016). "However, whether down-regulation of FUT4 can inhibit EMT in lung cancer is still unclear." (PMID 26636541, 2016). "Our results revealed that both FUT4 and EMT marker N-cadherin were consistently elevated in the lung cancer tissues, indicating there was an intrinsic linkage between them." (PMID 26636541, 2016). "Therefore, we hypothesized that FUT4 is an important target of Rg3′s inhibition EMT in lung cancer." (PMID 26636541, 2016). "The mRNA expression of lncMALAT1, STAT3, and FUT4 was significantly high in A549/T cells as compared with the non-resistant A549 lung cancer cells." (PMID 35281907, 2022).
lung carcinoma (continued). "The aim was also extended to gain insight into whether simultaneous inhibition of STAT3 activation and FUT4 fucosylation via ALT and Brv-A have any impact on functional role of lncRNA MALAT1 in A549/T lung cancer cells." (PMID 35281907, 2022). "After establishing the expected role of MALAT1, STAT3, and FUT4 in resistant and non-resistant lung cancer cells, we further studied the association of MALAT1 with STAT3 and FUT4 expression in A549/T cells." (PMID 35281907, 2022). "Our previous study showed that the downregulation of fucosyltransferase IV (FUT4) expression inhibited the biosynthesis of Lewis Y antigen (LeY), which inactivated EGFR and downstream signaling pathways to ultimately decrease EMT in lung cancer cells." (PMID 28798691, 2017). "These evidence showed that FUT4 could be a potential target for the regulation of EMT, which may be an attractive strategy in inhibiting invasion and metastasis in the treatment of lung cancer." (PMID 26636541, 2016). "To investigate whether down-regulating FUT4 expression inhibited migration, invasion and EMT in lung cancer, we analyzed the potential correlation between FUT4 and EMT in lung cancer tissues." (PMID 26636541, 2016). "FUT4 may also be related to multidrug resistance in lung cancer and may participate in chemoresistance to cisplatin by suppressing FOXO1-induced apoptosis in lung cancer." (PMID 37256139, 2023). "Several studies are previously conducted to discover the role of lncRNA MALAT1 in chemoresistance, however, how MALAT1 functions in the context of a therapeutic approach with special prominence to MALAT1/STAT3 and MALAT1/FUT4 axis in paclitaxel-resistant lung cancer is not well-known." (PMID 35281907, 2022). "However, whether Rg3 inhibits lung cancer EMT by down-regulating FUT4 mediated glycosylation is not clear." (PMID 26636541, 2016). "FUT4 expression shows a negative correlation with the overall survival in operable LUAD, and may induce lung colonization and distant metastases of lung cancer cells." (PMID 37256139, 2023). "However, it was not clear whether FUT4 and EMT are correlated in lung cancer." (PMID 26636541, 2016).
colorectal cancer (33 papers, 2012 to 2024). A primary or metastatic malignant neoplasm that affects the colon or rectum. "In adult cancers, such as breast and colorectal cancer, it has been demonstrated that overexpression of ST3Gal3 and FUT4 is associated with poor prognosis." (PMID 30344930, 2018). "However, whether this loss of FUT4 is really due to unknown genetic or epigenetic factors influencing fucosyltransferase-specific gene expression levels in the context of colorectal cancer remains to be elucidated by future studies." (PMID 30476078, 2019). "MALAT1 mediates fucosyltransferase 4 (FUT4)-related glycosylation in hypometastatic colorectal cancer cells and activates the PI3K/AKT/mTOR pathway, affecting the tumor microenvironment and allowing CRC to metastasize." (PMID 36552835, 2022). "Several target genes of miR-125a-5p had been reported, for example, miR-125a-5p suppressed bladder cancer progression through targeting FUT4, inhibited colorectal cancer invasion and migration by targeting TAZ and so on." (PMID 32308562, 2020). "Overexpression of FUT4 leads to the increase in CD15 expression and correlates with metastasis in colorectal cancer." (PMID 31104223, 2019). "In the present study, we exploited the CRISPR-dCas9-VPR system for transcriptional activation of certain α1-3 fucosyltransferase genes, Fut4 and Fut9, playing a major role in colorectal cancer pathogenesis." (PMID 30476078, 2019). "In all data sets, LY6G6D was highly expressed in colorectal cancer compared to normal tissues, whereas FUT4 expression levels, tended to be significantly higher in CRC than in normal mucosa in two out of three databases." (PMID 30670049, 2019). "FUT4 is increased in leukaemia, gastric, breast and colorectal cancer; UGT2B17 is increased in endometrial cancer; POFUT1 is increased in glioblastomas and oral squamous cell carcinoma, and MAN2A1 is decreased in glioblastoma." (PMID 30038662, 2018). "Furthermore, SMYD2-mediated regulation of the Erb-B2 receptor tyrosine kinase 2 (ERBB2)/fucosyltransferase 4 (FUT4) signaling pathway controls colorectal cancer growth." (PMID 39482529, 2024). "In colorectal cancer, FUT4 is down-regulated by miR-200c and by miR-26a/26b." (PMID 36555445, 2022). "Moreover, FUT4 regulation has also been elaborated in colorectal cancer where miR-26a/26b is sponged by MALAT1 to enhance the FUT4 fucosylation and promotes the metastasis via activation of PI3K/AKT pathway." (PMID 35281907, 2022). "In addition, transcriptional upregulation of FUT4, which increases cell-surface Lewis Y antigen levels, leads to chemoresistance in patients with colorectal cancer." (PMID 32948132, 2020). "Specifically, in colorectal cancer cells, increased levels of the fucosylated Lewisx antigen are attributed to the deregulated expression of pertinent fucosyltransferases, like fucosyltransferase 4 (FUT4) and fucosyltransferase 9 (FUT9)." (PMID 30476078, 2019). "Though FUT6 seems to have a preference for the sialylated substrate, here, the results point towards the expression of mainly non-sialylated Lewis antigens via action of fucosylytransferases FUT3 (Lewis A) and FUT4 or FUT6 (Lewis X) in the CDX1high colorectal cancer cell lines analyzed here." (PMID 30909444, 2019). "Similarly, the increased expression of ST3GAL4 and FUT4 was reported in colorectal carcinomas." (PMID 25923697, 2015). "However, it is still unknown whether increased expression of FUT4 and FUT9, influencing the abundance of α2-3-linked sialic acids on N-glycans, is associated with decreased Siglec binding to colorectal cancer cells and modulation of the anti-tumor immune response in vivo." (PMID 30476078, 2019). "To gain insights into the mechanisms that regulate CD15/FUT4 expression, we collected two independent publicly available gene-expression datasets involving a total of 436 colorectal cancer and 60 colon cancer cell lines." (PMID 26427914, 2015).
colorectal cancer (continued). "Despite the scarce importance in IBD differentiation, the oncogenic role of miR-142-3p is well known, which promotes cellular invasion in colorectal cancer cells by activating RAC1 and the onco-suppressive activity of miR-26a, and inhibits cell aggressiveness by regulating FUT4 in CRC." (PMID 32019170, 2020). "Conversely, the FUT4- and FUT9-mediated synthesis of DC-SIGN and MGL-1 ligands containing the Lewisx epitope hints to potential implication of these enzymes in the induction of an immunosuppressive tumor microenvironment in colorectal cancer." (PMID 30476078, 2019). "Additionally, the induction of complex N-glycan synthesis in MC38 cells upon FUT4 and FUT9 induction raises a possible role for these fucosyltransferases in the metabolic control of colorectal cancer cells." (PMID 30476078, 2019). "Therefore, we sought to transcriptionally activate the Fut4 and Fut9 genes in the well-known murine colorectal cancer cell line, MC38, which lacks expression of the FUT4 and FUT9 enzymes." (PMID 30476078, 2019). "However, the preferred carrier molecules of Lewisx, synthesized by FUT4 and FUT9 in colorectal cancer cells, have been scarcely studied so far." (PMID 30476078, 2019). "MALAT1 could also upregulate FUT4 expression and enhances fucoidan glycosylation and in laboratory studies, MALAT1 triggers the activation of the PI3K/AKT/mTOR pathway, thereby promoting colorectal cancer cell invasiveness." (PMID 39830506, 2024). "Although high expression of fucosylated epitopes has been observed in many human colorectal cancer cell lines, our MC38 wild type cells did not express any fucosylated type I or type II Lewis antigens on their cell surface and were completely devoid of Fut4 and Fut9 gene expression." (PMID 30476078, 2019). "However, the biosynthetic properties of the FUT4 and FUT9 enzymes and the potential effect of increased Lewisx expression on the glycosylation status of colorectal cancer cells have not been fully investigated yet." (PMID 30476078, 2019). "More specifically, we demonstrate here that de novo synthesis of the fucosylated Lewisx antigen by FUT4 and FUT9 leads to potent alterations in the N-glycome of colorectal cancer cells, with a negative impact exerted on core-fucosylation and the α2-3 sialylation levels." (PMID 30476078, 2019).
glioblastoma (33 papers, 2009 to 2024). The most malignant astrocytic tumor (WHO grade IV). "In addition, SSEA1 (Stage-Specific Embryonic Antigen 1, fucosyltransferase 4, CD15), a glioblastoma tumor stem cell marker, was investigated." (PMID 35954348, 2022). "Importantly, we found a correlation between the expression of stemness markers (CD44 and FUT4 (CD15)) with ABCC3 in glioblastoma." (PMID 36585418, 2022). "We found a similar correlation between CD44, FUT4 (CD15) and ABCC3 expression across glioblastoma patient datasets." (PMID 36585418, 2022).
COVID-19 (24 papers, 2020 to 2025). A disease caused by infection with severe acute respiratory syndrome coronavirus 2. "Patients with severe COVID-19 had a higher proportion of so-called low density neutrophils within the mononuclear cell fraction, including such immature neutrophil subsets as FUT4 (CD15)+CD63+CD66b+ pro-neutrophils and ITGAM (CD11b)+CD101+ pre-neutrophils." (PMID 35632823, 2022).
medulloblastoma (19 papers, 2011 to 2025). A malignant, invasive embryonal neoplasm arising from the cerebellum. "We verified that the stem culture condition increased the expression of well-established MBSC markers CD133, FUT4, SOX2, NESTIN in all cell lines compared to the expression in medulloblastoma cells cultured in the presence of serum." (PMID 32316671, 2020).
melanoma (19 papers, 2010 to 2025). A malignant, usually aggressive tumor composed of atypical, neoplastic melanocytes. "Similar effects of Rg3 have also been described in melanoma, where Rg3 affects FUT4 expression and inhibits the FUT4-associated EGFR/MAPK signaling pathway." (PMID 29527514, 2018). "We found that Rg3 did not only inhibit A375 melanoma cell proliferation in a dose-dependent manner, but also decreased the expression of fucosyltransferase IV (FUT4) and its synthetic product Lewis Y (LeY), a tumor-associated carbohydrate antigen (TACA)." (PMID 25672851, 2015). "Notably, our findings are consistent with further gene set enrichment analysis (GSEA) that revealed a strong associative trend between FUT4 expression and androgen response signatures in a large-cohort melanoma patient expression dataset (TCGA_SKCM)." (PMID 38326303, 2024). "By delineating key androgen-triggered signaling that enhances metastatic aggressiveness, our findings help explain sex-associated clinical outcome disparities and highlight AR/FUT4 and its effectors as potential prognostic biomarkers and therapeutic targets in melanoma." (PMID 38326303, 2024). "In this process, AR-driven FUT4 signaling alters cell–cell adhesion by disrupting N-cadherin-catenin-based junctional complexes between melanoma cells, which impacts adherens junctions (AJs) and promotes cellular spread." (PMID 40940929, 2025). "The fucosylation of the L1 cell adhesion molecule (L1CAM) by AR-activated FUT4 further promotes metastatic progression in melanoma." (PMID 40564107, 2025). "While the mechanism of AR’s observed effects is not entirely understood, recent data show that AR signaling enhances melanoma invasiveness by upregulating fucosyltransferase 4 (FUT4), leading to the dysregulation of cellular junctions." (PMID 40564107, 2025). "VIM2, a sLex paralog, was nearly undetectable in melanoma cells; however, among CD15 and CD15s glycan epitopes, only CD15 was increased in melanoma cells ectopically expressing FUT4." (PMID 38326303, 2024). "Integrated proteomics analysis identified L1CAM as a key downstream effector fucosylated by FUT4, which is required for AR-FUT4-promoted melanoma metastasis." (PMID 38326303, 2024). "Further, FUT4 levels are significantly higher in metastatic lesions as compared to primary melanoma specimens (TCGA_SKCM and GSE8401 datasets)." (PMID 38326303, 2024). "To delineate the functional contribution of AR-FUT4 signaling in driving melanoma metastasis in vivo, we implanted EV or FUT4-OE WM793 melanoma cells into immunodeficient male NSG mice." (PMID 38326303, 2024). "Together, these findings demonstrate a crucial role for FUT4 in mediating androgen/AR-stimulated melanoma invasiveness and strongly support the role of the AR-FUT4 axis in promoting melanoma metastasis." (PMID 38326303, 2024). "Rather, consistent with the observed 2FF-increased and FUT4-OE-decreased AJ formation, we found that 2FF and FUT4-OE suppressed and enhanced, respectively, the motility of melanoma cells." (PMID 38326303, 2024). "We next sought to delineate the functional contributions of L1CAM to AR-FUT4-regulated melanoma biology by generating melanoma cells that were simultaneously modified for FUT4 (overexpression) and L1CAM (knockdown)." (PMID 38326303, 2024). "Knockdown of FUT4 in melanoma cells also resulted in decreased Lewisy expression and reduced EGFR phosphorylation, and inhibited melanoma cell proliferation through EGFR-mediated MAPK signaling pathway." (PMID 34069424, 2021). "It has been shown that NF-κB/p65-dependent transcriptional regulation of FUT4 modulates human melanoma cell proliferation." (PMID 34440905, 2021). "A more recent report confirmed the importance of FUT4 in migration and invasion of human melanoma cells that occur through the activation of the PI3K/AKT signaling pathway." (PMID 34440905, 2021).